EGFR (epidermal growth factor receptor)
Diseases named in the same sentence as EGFR in open-access papers (continued):
Sharing a sentence is not in itself a finding about the gene and the disease.
colon carcinoma (continued). "The antitumor efficacy of UCB-NK cells against cetuximab-resistant human EGFR+ RASmut colon cancer cells was further confirmed in an in vivo preclinical mouse model where UCB-NK showed enhanced antitumor cytotoxicity against colon cancer independent of EGFR and RAS status." (PMID 28220124, 2017). "Pollack at al has previously reported that EGFR inhibitors synergistically up-regulated the expression of antigen presenting proteins in one of squamous cell carcinoma (SCC) of head and neck cancer cell lines among other cell lines originated from various cancer such as melanoma or colon cancer." (PMID 27467256, 2016). "This may imply that the sensitivity of RAS WT colon cancer for EGFRi is not an acquired oncogene-addiction, but merely represents the dependency of normal colon (stem) cells on EGFR signaling activity." (PMID 27845624, 2016). "Furthermore, in vitro and in vivo data suggests that colon cancer cells, unlike melanoma cells that express low levels of EGFR, are particularly prone to this engage in this rescue mechanism." (PMID 26525348, 2015). "Therefore, the crosstalk between EGFR and COX-2 may also have an important role in regulating stemness-related pathways, such as wnt/β-catenin pathway, in colon cancer." (PMID 26107817, 2015). "Activation of the RAS pathway has been described as a mechanism of primary or secondary resistance in colon cancer, where the presence of KRAS activating mutations in the primary tumor is a negative predictive factor of response to the anti-EGFR monoclonal antibodies cetuximab and panitumumab." (PMID 25691052, 2015). "Tyrosine kinase inhibitors of EGFR have not shown efficacy in colon cancer patients yet." (PMID 26318427, 2015). "In fact, the three mAbs approved for colon cancer immunotherapy, bevacizumab and cetuximab or panitumumab, are not completely specific for target colon cancer, as they recognize the vascular endothelial growth factor (VEGF) or the epidermal growth factor receptor (EGFR), respectively." (PMID 25883890, 2015). "Additionally, we further confirmed that the interaction between MET and SRC and the formation of MET/SRC/EGFR complex contributed to constitutive MET activation, providing a rationale for combinatorial inhibition of EGFR and MET or EGFR and SRC in therapy targeting colon cancer." (PMID 24714091, 2014). "Therapies available for treatment of colon cancer include surgery, radiation therapy, chemotherapy, immunomodulatory therapy, and molecularly targeted therapies such as anti-vascular endothelial growth factor receptor (VEGFR) and anti-epidermal growth factor receptor (EGFR) therapy." (PMID 24874286, 2014). "While some studies report the associations between the co-expression of HER-2/HER-4 or HER-3/HER-4 and late tumour stages, to our knowledge the significant co-expression of EGFR/HER-4 with poorer disease-free survival in colon cancer patients has not been previously reported." (PMID 24609222, 2014). "Therefore, we still cannot rule out the possibility that, in addition to EGFR, other molecules in colon cancer cells are involved in regulating cancer stem-like cell properties." (PMID 25003232, 2014). "Currently, major efforts have been made to develop some anticancer therapies based on the small molecules that specifically target DNA demethylating protein or EGFR, whereas, not much information is known about the combined effects of EGFR inhibitors and demethylating agents in colon cancer." (PMID 24874286, 2014). "This possibility is illustrated by a study in intestinal epithelial cell-6 cells (IE6) and Caco-2 colon cancer cells in which PAR2-driven prostaglandin E-2 (PGE2) production is a consequence of increased COX-2 expression, that results from a metalloproteinase-dependent transactivation of the EGFR." (PMID 24215724, 2013).
colon carcinoma (continued). "Similar to this EGFR/HER2-independent role in NF-κB activation, lapatinib has also been reported to up-regulate the expression of pro-apoptotic TRAIL death receptors DR4 and DR5 through an off-target mechanism in colon cancer cells and, thus, sensitizes these cancer cells to TRAIL-induced apoptosis." (PMID 24216290, 2013). "The FET colon cancer cell line which normally does not form subcutaneous xenografts in athymic mice becomes highly tumorigenic after TGFα (transforming growth factor-α) transfection to generate constitutive EGFR (epidermal growth factor receptor) activation." (PMID 22672900, 2012). "In colon cancer, the negative predictive value of KRAS mutation status for the anti-EGFR antibodies efficacy has been reported first in retrospective studies then definitively confirmed by retrospective analysis of tumors of patients included in large prospective trials." (PMID 24212636, 2011). "Using H508 human colon cancer cells with high-level expression of CHRM3 we identified bile acids as CHRM3 agonists and revealed that, as with ACh, proliferative actions of bile acids require cross-talk between CHRM3 and epidermal growth factor receptors (EGFR) and post-receptor ERK1/2 activation." (PMID 24212649, 2011). "Furthermore, no studies have addressed the prognostic effect of phospho-EGFR in colon cancer patients." (PMID 19997103, 2010). "FOXD3 gene knockdown could activate the expression of EGFR/ERK signaling pathway-related proteins and inhibit/promote the expression of EMT-related proteins, which in turn promoted the proliferation and metastasis of LoVo cells from colon cancer bone metastases." (PMID 37151068, 2023). "To address this hypothesis, we compared TIL and paired PBMC function, by analyzing NK cell IFNγ production and degranulation activity in the presence of the MHC class I non-expressing K562 cells or with EGFR+ SW480 colon carcinoma target cells in the presence of Cetuximab in an ADCC assay." (PMID 36341402, 2022). "In addition, ADAM17 also promotes STAT3 activation by induction of EGFR/IL-6 transduction signaling pathways, which ultimately lead to tumor progression; inhibition of the ADAM17/IL-6/STAT3 signaling axis significantly attenuated the growth of colon cancer cells." (PMID 36466812, 2022). "Furthermore, ECGC, weakens the Tyr1068 EGFR phosphorylation so affecting the receptor recycling after lipid raft alteration, inhibiting the downstream effectors ERK and Akt and the transcriptional activity of AP-1, c-fos, NF-kB, and cyclin D1 promoters in colon cancer cells." (PMID 36428610, 2022). "More importantly, we found that left-side CRC and right-side colon cancer have distinct immune landscapes, and that this immune landscape might, to some extent, explain the primary CRC location-specific differences in prognoses and responses to anti-VEGF and anti-EGFR agents." (PMID 30042763, 2018). "Furthermore, EGFR-stimulation induces COX-2 and PGE2 production in OSCC cell lines, which may further increase AREG expression due to EGFR-cross activation, as shown for colon cancer cell lines." (PMID 27669890, 2016). "Interestingly, the non-breast derived brain metastases showed similarly high activation of the MAPK pathway together with over-expression (3+ stain) of EGFR (in 9/11 (81%) metastases (a prostate and one colon carcinoma did not) but in the absence of HER3 activation (0/11)." (PMID 20604919, 2010). "Recombinant extracellular domain of EpCAM induces EGFR phosphorylation and MAPK and Akt activation in the absence of EGF in colon cancer HCT116, Colo205 and HT-29 cells and in mesenchymal stem cells." (PMID 39594667, 2024). "We previously reported that ST6GAL1 sialylates and activates EGFR in PDAC, ovarian, and colon cancer cell lines, as well as in nonmalignant cells, although an inhibitory effect of sialylation has also been reported." (PMID 37643018, 2023).
colon carcinoma (continued). "On the other hand, cell proliferation was not stimulated by BAs in CHO colon cancer cells that express only CHRM3 and SNU-C4 cells that express only EGFR." (PMID 36919835, 2023). "While this secretion is comparable to that of the colon cancer CTC cell line CTC‐MCC‐41, CTC‐ITB‐01 does not secrete OPG (osteoprotegerin), EGFR (epidermal growth factor receptor) or FGF2 (fibroblast growth factor‐2) characteristic for CTC‐MCC‐41." (PMID 32667137, 2020). "By contrast, concomitant inhibition of β1 integrin and EGFR in HNSCC spheroids and colon carcinoma does not improve radiotherapy efficacy." (PMID 31109009, 2019). "While cetuximab monotherapy was not effective against EGFR− RASwt, EGFR+ RASmut, and EGFR+ BRAFmut cells, A-PBNK were able to initiate lysis of EGFR+ colon cancer cells irrespective of RAS or BRAF status." (PMID 28220124, 2017). "Consistent with preclinical studies, increased levels of HGF in colon cancer patients with WT KRAS, and in NSCLC patients correlate with lack of response to EGFR inhibitors." (PMID 28420162, 2017). "Small molecules inhibiting EGFR such as erlotinib or gefitinib as well as anti-EGFR antibodies such as cetuximab were successfully tested in non-SCLC, head and neck, pancreatic and colon cancer." (PMID 20683448, 2010). "Drug-induced tyrosine phosphorylation of JAK2 and Src attenuated EGFR and STAT3 tyrosine phosphorylation, but EGFR tyrosine kinase inhibitor therapy (gefitinib) suppressed STAT3 phosphorylation in HCT116 colon cancer cells without influencing JAK2 or Src phosphorylation." (PMID 38397437, 2024). "Cellular localization (colon cancer cells) and competitive binding studies showed that conjugates 59 and 60 with LARLLT peptide showed specific binding with the epidermal growth factor receptor (EGFR) protein, compared with the conjugates 61 and 62, not containing peptide." (PMID 35209191, 2022). "As there are currently no other treatment alternatives for this colon cancer subgroup, in cases with MSS status, further evaluation of this combination inhibiting EGFR and MEK might be considered." (PMID 34885128, 2021). "Because colon cancer cells with wild type KRAS could be transformed by WSTF/NRG3, they would be not sensitive to the targeted inhibition of EGFR." (PMID 27449290, 2016). "In vitro cytotoxicity experiments using colon cancer primary tumors and cell lines COLO320, Caco-2, SW620, SW480 and HT-29, demonstrated that PBNK cells are cytotoxic for a range of tumor cells, regardless of EGFR, RAS or BRAF status and at low E:T ratios." (PMID 27314237, 2016). "Moreover, phleomycin is only radiomimetic, and unlike EGFR inhibition by monoclonal antibodies, EGFR inhibition by tyrosine kinase inhibitors (TKI) such as erlotinib in colon cancer has not achieved wide clinical utility." (PMID 25134433, 2014). "Two recent studies on colon cancer that systematically modelled the response of the RAS/PI3K signalling pathway to inhibition of EGFR by cetuximab revealed strong negative feedback loops between ERK and EGFR." (PMID 24411063, 2014). "Subgroup analyses based on EGFR expression and tumor location showed significant differences in terms of DFS in the patients with right- and left-sided colon cancers and in terms of OS the in patients with left-sided colon cancers, but not in those with right-sided colon cancers." (PMID 29383110, 2017). "Thus, the authors recommend that BRAFV600E mutant colon cancer with no current targeted treatment options available may benefit from combinatorial BRAF and EGFR inhibitors." (PMID 26525348, 2015). "Metastatic colon cancers are routinely tested for mutant KRAS to determine suitability for biologic adjuvant therapy with the anti-epidermal growth factor receptor (EGFR) antibody, cetuximab, as surprisingly, patients with mutant KRAS fared worse with anti-EGFR therapy than without treatment." (PMID 26497569, 2015).
melanoma (822 papers, 2006 to 2026). A malignant, usually aggressive tumor composed of atypical, neoplastic melanocytes. "A KEGG enrichment analysis revealed numerous pathways associated with pigmentogenesis, such as “Melanoma”, “EGFR tyrosine kinase inhibitor resistance”, and “Wnt signaling pathway”." (PMID 39857428, 2025). "EGFR signaling has been implicated in melanoma progression through alternative mechanisms such as copy number variations and splice variants." (PMID 40652269, 2025). "Nevertheless, EGFR expression has been documented in a subset of melanoma cells and is associated with more aggressive, therapy-resistant phenotypes." (PMID 41516067, 2025). "EGFR and its pathway promote development and progression of several cancers, and it associates with poor prognosis in melanoma." (PMID 40954493, 2025). "Studies of melanoma cell lines that express BRAF mutation indicate a mechanism related to EGFR overexpression and activation of the MAPK and PI3K-AKT pathways after drug administration." (PMID 38396984, 2024). "For instance, EGFR gene amplification has been linked to a worse prognosis, suggesting its importance in melanoma." (PMID 38534309, 2024). "Four patients diagnosed with ovarian cancer, melanoma, sarcoma, or cholangiocarcinoma received afatinib based on an EGFR or ERBB3 mutation." (PMID 37175010, 2023). "Downregulation of Ack1 in these cells causes a decrease in EGFR degradation, as evidenced by in vitro and in vivo melanoma models." (PMID 36980241, 2023). "Other studies have also demonstrated the diagnostic utility of CSF ctDNA analysis, with mutation profiles generally consistent with the primary tumour type (e.g., NRAS and BRAF mutations from melanoma patients and EGFR mutations for lung BrM patients)." (PMID 35225863, 2022). "In recent years, interest has increased in the use of EGFR-targeting agents to treat malignant melanoma, which is responsible for most deaths caused by skin cancers." (PMID 36432639, 2022). "Sometimes, mutations in the EGFR gene cause EGFR proteins to be made in higher than normal amounts in a number of cancer cell lines, including those from breast, colon, non-small cell lung, renal, melanoma, ovarian, and prostate cancers." (PMID 36297760, 2022). "The expression of various receptor tyrosine kinases, including AXL, PDGFRB, and EGFR, in cutaneous melanoma occurs in MITFlow melanoma cells with a proinvasive potential and has been associated with BRAF/MEK inhibitor resistance." (PMID 33916908, 2021). "Mutations in EGFR have been linked to developing various diseases, including diverse cancers, including melanoma and hepatocarcinoma (HCC)." (PMID 34067095, 2021). "In summary, LRIG1 is a conserved regulator of EGFR signaling that is negatively regulated during early melanoma development and that associates with survival in an EGFR-dependent manner at the metastatic stage." (PMID 33947959, 2021). "The current study shows that LRIG1 expression is associated with survival in an EGFR-dependent manner and that the association is lost in melanoma subtypes characterized activating mutations downstream of EGFR." (PMID 33947959, 2021). "The ERK1/2 pathway communicates signals from surface receptors like EGFR into the nucleus that is also linked to Raf mutations, known to occur in up to 90% of patients with melanoma." (PMID 34360915, 2021). "Further, EGFR expression is upregulated in some human melanoma cell lines, and inhibition of STAT5 causes increased apoptosis." (PMID 34067095, 2021). "In melanoma, elevated EGFR activity is mostly caused by transcriptional regulation, but not by the appearance of oncogenic EGFR mutations." (PMID 33916908, 2021). "The expression of various receptor tyrosine kinases, like AXL, PDGFRB, and EGFR, in cutaneous melanoma occurs in MITFlow melanoma cells with a pro-invasive potential and has been associated with BRAF/MEK inhibitor resistance." (PMID 34360915, 2021).
melanoma (continued). "Oncogenic BRAF, NRAS, NF1 mutations can activate the tyrosine kinase receptor EGFR resulting in enhanced ERK1/2 phosphorylation in melanoma." (PMID 34360915, 2021). "Ectopic overexpression of EGFR is sufficient to cause vemurafenib resistance in melanoma cells in vitro." (PMID 33947959, 2021). "In human melanocytes, MAPK signaling causes reduction of MITF and increases ERBB3, FOXD3 and NRG1 transcription factor gene expression, with NRG1 and FOXD3 also further upregulating ERBB3, which can heterodimerize with EGFR causing melanoma metastasis." (PMID 34067095, 2021). "It was just recently described that long-term vemurafenib treatment in BRAF-mutant melanoma cells can lead to increased migration in association with elevated EGFR expression." (PMID 32613561, 2020). "Previous studies have found that the frequency of oncogenic mutations in the EGFR gene is closely related to the occurrence of melanoma." (PMID 33178610, 2020). "EGFR expression is more frequent in metastatic melanoma and has been associated with undifferentiated phenotype of melanoma cells." (PMID 31936151, 2020). "To analyse the role of EGRF in regulation of invasive abilities of melanoma cells, we generated variant of A375 cell line with stably up‐regulated expression of EGFR (A375 EGFR), in comparison with cells transfected with empty plasmid A375 MOCK." (PMID 31638339, 2019). "It was shown that ectopic expression of EGFR in melanoma cells was sufficient to cause vemurafenib (BRAF inhibitor) resistance." (PMID 31649529, 2019). "This drug has shown in vitro and in vivo efficacy in combination with targeted therapies like EGFR inhibitors in EGFR mutation-positive NSCLC or BRAF/MEK inhibitors in BRAF mutation-positive melanomas." (PMID 31150457, 2019). "These drugs are currently approved for treating advanced NSCLC with EGFR mutations and melanoma with B-RAF V600E mutation, respectively." (PMID 29416679, 2018). "The combination of BRAF/MEK inhibitors have been shown to extend PFS and OS in BRAF-mutated metastatic melanoma but melanoma cells express low levels of EGFR activity." (PMID 30519549, 2018). "We have demonstrated that RUNX2-deficient melanoma cells display a significant decrease in three receptor tyrosine kinases, EGFR, IGF-1R and PDGFRβ." (PMID 27102439, 2016). "They further showed that expression of EGFR is sufficient to cause resistance to Vemurafenib in melanoma cells." (PMID 26393652, 2015). "In our study, kinase substrates encoding for EGFR and PDGFRβ were found to be significantly differentially affected by ex-vivo vemurafenib in melanoma tumors harboring BRAF(V600E) and BRAF wild-type." (PMID 24023633, 2013). "Further studies are needed to establish the large scale distribution of the syndrome and confirm that the lesions reported here are the same as the melanoma in Xiphophorus, by assessing mutation of the EGFR gene, Xmrk." (PMID 22870273, 2012). "Another observed state is the undifferentiated phenotype, marked by low levels of SOX10 (SRY-related HMG-box 10) transcription factor and elevated expression of tyrosine kinases such as AXL and EGFR, associated with aggressive and drug-resistant melanoma subtypes." (PMID 40872623, 2025). "Some RTK family members like EGFR may be expressed in MITF-low melanoma cells, and under this circumstance, the EGFR expression is linked to a pro-invasive and pro-metastatic melanoma phenotype with resistance to BRAF/MEK inhibitors." (PMID 36747120, 2023). "It is plausible that EGFR mutations that occur in a certain percentage of melanomas may contribute to primary resistance." (PMID 35565444, 2022). "All these studies supported our finding that EGFR is a risk gene for melanoma prognosis." (PMID 34809598, 2021).